VIM (vimentin)
Diseases named in the same sentence as VIM in open-access papers (continued):
Sharing a sentence is not in itself a finding about the gene and the disease.
cancer (continued). "Because HMGA2 plays a pivotal role in cancer metastasis progression by regulating epithelial–mesenchymal transition (EMT) in various cancers, we detected the expression of EMT target genes, such as N-cadherin, E-cadherin and vimentin by western blot analysis." (PMID 35871166, 2022). "Among them, studies conducted on poorly differentiated metastatic cancer cells revealed the presence of Vimentin within their nuclear matrixes, while it was no longer detected upon induction of cell differentiation." (PMID 35100428, 2022). "The upregulation of SOX9 expression reduces the expression of E-cadherin and increases the expression of vimentin and α-SMA, thereby promoting the invasion and metastasis of cancer cells and decreasing the survival of patients with CCA by conferring chemoresistance." (PMID 36300097, 2022). "Moreover, studies have demonstrated that FSCN1 also promoted EMT in cancers including HCC, and as predictable its suppression significantly suppressed vimentin expression, a key marker of EMT." (PMID 35081125, 2022). "Vimentin, functions as a critical protein involved in cell attachment, migration, signaling, is responsible for maintaining cell shape and stabilizing cytoskeletal interactions, and mediating the EMT process of cancer cells." (PMID 35436995, 2022). "CXCL8 and LAPTM5 proteins have been reported to promote cell activity, TMEM156 and LGALS1 proteins enhance cell invasion, VIM and LGALS1 proteins induce cell migration, FABP5 and SRGN proteins activate cancer metastasis, and the DEFB4A protein regulates immunity in human cancers." (PMID 35632763, 2022). "While vimentin is a well-established marker of the negative prognostic process defined in cancer as epithelial-to-mesenchymal transition, little is known about its expression in non-neoplastic or benign tumoural epithelia." (PMID 35737305, 2022). "The post-translationally modified forms of Vimentin intermediate filaments have several implications in host-pathogen interactions, cancers, and non-malignant lung diseases." (PMID 35573702, 2022). "In our study, we showed that PA2G4 enhanced the migration and invasion ability of cancer cells, induced a rearrangement of F-actin and modulated the expression of EMT-related molecular markers (E-cadherin, N-cadherin, occluding, Vimentin, α-SMA and ZO-1) as well as TFs (ZEB1, ZEB2 and Snail)." (PMID 35526051, 2022). "Similarly, no significant expression changes were observed in the studied mesenchymal markers in the resistant cancer cells such CDH2, VIM, ZEB1, ZEB2, SLUG, TWIST1 that which are upregulated in completed EMT." (PMID 35523936, 2022). "In addition, activation of MET regulates E-cadherin and vimentin to induce EMT and promotes cancer cell proliferation through activating downstream targets such as c-Myc." (PMID 35301291, 2022). "In late-stage cancer, cells seem to become resistant to its anti-mitotic effects and TGFB1 was instead observed to stimulate EMT by upregulating mesenchymal markers (e.g., VIM, CDH2) and downregulating epithelial markers (e.g., CDH1)." (PMID 35565214, 2022). "Furthermore, alcohol can directly upregulate the expression of vimentin and matrix metalloproteinases MMP-2, MMP-7, and MMP-9, which are known to promote an epithelial–mesenchymal transition, cancer cell aggressiveness, and extracellular remodelling." (PMID 35276890, 2022). "Nonetheless, unlike studies on other cancers, our clinical data suggested a better prognosis for vimentin-positive patients with EC." (PMID 35320951, 2022). "In human cancer, the activation of the EMT process is related to advanced disease, which was demonstrated by the transition of epithelial biomarkers (E-cadherin) to mesenchymal biomarkers (Vimentin)." (PMID 35761331, 2022).
cancer (continued). "Since the key to invasive migration of cancer cells is the occurrence of Epithelial-Mesenchymal Transition (EMT), and the markers of EMT occurrence include the reduction of the epithelial marker E-cadherin, and the upregulation of N-cadherin and Vimentin." (PMID 36203485, 2022). "We additionally studied the vimentin expression in oral precancers and cancers compared with normal tissues." (PMID 35498535, 2022). "In recent years, our understanding of the role of Vimentin intermediate filaments as a crucial player in the development of cancers by regulating non-EMT-dependent pathways has also evolved." (PMID 35573702, 2022). "Conversely, LINC02470 and SMAD3 were expressed at lower levels in low-grade cancer cells or nontumor cells with higher epithelial-like traits, such as higher E-cadherin and cytokeratin 18 expression but lower N-cadherin and vimentin expression." (PMID 35205713, 2022). "Studies have reported that some cancer-derived epithelial cells express vimentin, but normal epithelial cells are keratin skeletons and do not express Vimentin." (PMID 35013490, 2022). "One of the cellular hallmarks of carcinoma malignancy and aggressiveness is epithelial to mesenchymal transition (EMT), which involves the remodeling of adhesion molecules, with epithelial E-cadherin downregulated and replaced by N-cadherin and/or vimentin." (PMID 35312942, 2022). "Further, our co-expression analysis also showed that key EMT-related factors such as MMP2, MMP9, CDH2, TGFB1, and VIM were highly expressed when CHN1 was highly expressed, while CDH1 was expressed at lower levels, suggestive of a potential cancer-promoting function of CHN1." (PMID 34152250, 2021). "TGFβ can induce EMT in cancer cells via upregulation of STAT3, vimentin, and FN1." (PMID 33917306, 2021). "Moreover, the expression switch from E-cadherin to N-cadherin in cancer tissues suggested the activation of EMT, along with the overexpression of vimentin, an important EMT marker." (PMID 34589516, 2021). "A careful examination of our results does not disagree with this assessment if one is examining cancer cells in isolation and focuses on vimentin as the only mesenchymal marker." (PMID 34375938, 2021). "It has been reported that Vimentin upregulation during EMT enhances tumorigenesis via targeting 14–3-3-mediated cell cycle control, and increases the migratory and invasive capacity of cancer cells by stabilizing scaffold protein SCRIB." (PMID 33530981, 2021). "Although serum vimentin expression has been reported for various cancers, these previous studies did not emphasize the significant role of extracellular vimentin in cell proliferation." (PMID 34299089, 2021). "However, the role of vimentin and EMT for cancer cells that intravasate into the bloodstream and extravasate into the metastatic site remains unresolved." (PMID 33691719, 2021). "Vimentin is a cytoskeletal protein to compose intermediate filament and is of great significance in epithelial-to-mesenchymal transition (EMT), and vimentin overexpression is identified and recognized as a prerequisite for the metastasis of human cancers." (PMID 34818974, 2021). "EMT is a crucially phenotypic plasticity process for migratory and invasive properties in cancer, blocking of TRIM37 significantly resulted the downregulation of mesenchymal cell markers of N-cadherin and Vimentin, as well as the upregulation of epithelial marker Claudin-1." (PMID 34130705, 2021). "In conclusion, this study revealed that RUNX1 plays an essential role in the development of replacement pattern vessel co-opting CRCLM lesions through regulation of its downstream molecules including ARP2/3, vimentin, and TSP1, which facilitate cancer cell motility." (PMID 34376784, 2021). "VIM and MMP2 are also markers of CAFs, which promote cancer progression and metastasis." (PMID 33747932, 2021).
cancer (continued). "The changes of intermediate filament Vimentin and F-actin indicated that CTSS could regulate single cell skeleton, and intrigue cancer cell transforming into a state with high movement ability." (PMID 33613746, 2021). "In this review, we discuss various aspects of the pathophysiological mechanisms and regulation of type-3 EMT, and the driving role of vimentin as an upstream and/or downstream effector in signalling feedback loops in regulating and sustaining EMT, cancer invasion and metastasis." (PMID 34638469, 2021). "OPRK1 knockdown could inhibited cell viability and migration in cancer cells, accompanied with the decreased proteins and genes expression of N-cadherin, Snail, MMP2 and Vimentin, while the E-cadherin expression was increased." (PMID 34461834, 2021). "Vimentin is a main component of IFs and is found in focal adhesions and could be a substrate of PLK1 during cancer invasion." (PMID 33963314, 2021). "Recently, vimentin and E-cadherin were shown to be prognostic markers in some malignant tumors but were not evaluated in pNETs." (PMID 33789624, 2021). "These MCF-7 cancer cells overexpress IGF-1R, which might lead to more binding of vimentin to the cell membrane, and a block (i.e., decreased permeability) of the paracellular junctions." (PMID 34299089, 2021). "The CTCs in the peripheral blood from HRP and cancer patients were enriched and identified based on the positive sorting method by epithelial cell adhesion molecular (EpCAM) liposome magnetic bead (Ep-LMB) and Vimentin liposome magnetic bead (Vi-LMB)." (PMID 34168982, 2021). "Similarly, the transfection of miRNA-29b into an invasive cancer cell line from the submaxillary salivary gland reverses EMT gene expression, increases E-cadherin, and decreases N-cadherin and Vimentin." (PMID 33806618, 2021). "Functionally, the knockdown of AFAP1-AS1 may inhibit proliferation and invasion, and decrease Twist1 and Vimentin expression in GBC cell lines, indicating that AFAP1-AS1 may participate in cancer progression." (PMID 34575316, 2021). "Vimentin is an important marker for the epithelial-mesenchymal transition in tissues (EMT), a phenomenon where cells undergo transition from epithelial to mesenchymal phenotype, ultimately leading to cancer metastasis." (PMID 33863886, 2021). "Cancer cell migration and invasion rely on EMT, during which epithelial markers (E-cadherin, ZO-1, and Occludin) are downregulated, whereas mesenchymal markers (vimentin, N-cadherin, and Fibronectin) are upregulated." (PMID 33757532, 2021). "It was proposed that EMT can transform non-CSCs into cancer stem cells, which are invariably vimentin-positive." (PMID 34638469, 2021). "Expression of TWIST1 and ZEB2 was largely absent in cancer cells, and, in 6 of the 8 cancer types, even the 95th percentile of Vimentin expression levels in cancer cells was lower than its average expression level in CAFs." (PMID 33972543, 2021). "Moreover, the expression of E-cadherin was increased and the expressions of N-cadherin and vimentin were decreased under the CTD treatment, supporting that the migration and invasion of cancer cells was suppressed." (PMID 34299129, 2021). "In both cell lines, VIM-AS1 and Vimentin expression levels were prominently occasioned by TGFβ1 incentive in a concentration-dependent manner, indicating that VIM-AS1 is related to EMT in bladder cancer and cancer metastasis." (PMID 33902589, 2021). "Moreover, the CMCAFs treatment induced the expression of EMT and cancer stemness markers in NOZ and GBC-SD cells, as revealed by reduced E-cadherin expression and increased vimentin, Sox2, CD44, Nanog and Oct4 expression." (PMID 33407730, 2021). "Recent studies also associate it with epithelial to mesenchymal transition (EMT), a biological phenomenon involved in the early progression of cancer metastasis, and the modulation of EMT regulators like Vimentin, Claudin-1 and other transcription factors, playing a dual role in EMT." (PMID 34440232, 2021).
cancer (continued). "Importantly, in most studies Vimentin and the EMT TFs were expressed at very low levels in the cancer cells and much more highly in CAFs, with the notable exception of SNAI2 in HNSCC." (PMID 33972543, 2021). "In addition, the IsoMAG IMS system was shown to allow the use of variable cancer/CTC markers, such as cell surface vimentin." (PMID 34829387, 2021). "The epithelial phenotype of cancer cells is governed by claudin-1 (CLDN1), claudin-7 (CLDN7), and E-cadherin (CDH1) genes, while the mesenchymal phenotype is regulated by ZEB1, SNAI1, SNAI2, and Vimentin (VIM) genes." (PMID 33670804, 2021). "We have also highlighted the reported damage to the vimentin gene in cancers, although how the damaged vimentin helps in cancer growth and spread is not known." (PMID 34638469, 2021). "Carcinomas are tumors of epithelial origin that often do not express vimentin because of their acute epithelial status." (PMID 34198671, 2021). "The ability of cancer cells to undergo partial EMT, rather than complete EMT and to maintain the expression of both E-cadherin and vimentin poses a higher metastatic risk." (PMID 32174917, 2020). "Malignant tumors grow out of control, obstructing the oxygen supply, leading to HIF-1α overexpression, and inducing cancer cell EMT, during which E-cadherin is downregulated and Vimentin is upregulated." (PMID 33062005, 2020). "UWG01CTC had no detectable EpCAM, mesenchymal (NCAD, Vimentin), or cancer stem cell marker (CD44, CD133, ALDH1)." (PMID 31953491, 2020). "The immunofluorescence analysis shows a significant increase of fluorescence intensity index (p < 0.001 versus control cells) of vimentin and FZD10 upon exposure of HCEC-1CT cells to exosomes derived from both the two cancer cell lines, at each investigated incubation time." (PMID 32933173, 2020). "Moreover, as the phenotype of EMT is correlated with the metastasis of cancers, two EMT biomarkers, E-cadherin and Vimentin were detected in ESCC cells transfected with SPARC siRNAs using western blotting." (PMID 31897236, 2020). "Simultaneously, it seems that vimentin does not need to be present in the invading cancer cells to facilitate metastasis formation." (PMID 31940801, 2020). "We found that blockade of Gas6 partially reduces vimentin protein expression in cancer cells, although this decrease was not statistically significant." (PMID 32174917, 2020). "Considering that cancer cell metastasis always accompanied by EMT, we then examined the influence of LINC01116 on the EMT process in BCa cells by measuring the expression of E-cadherin, N-cadherin, and Vimentin." (PMID 33311496, 2020). "Considering EMT is an important step in the process of cancer invasion and metastasis, we examined whether DJ-1 could alter the expression of the EMT markers E-cadherin and Vimentin." (PMID 32366371, 2020). "On the other hand, vimentin, an EMT marker, is one of the intermediate filaments that mainly functions to maintain cell integrity and involved in the cell migration and invasion of metastasizing cancer cells." (PMID 33330495, 2020). "Previous studies have shown that ectopic LEF1 expression enhances the expression of epithelial-mesenchymal transition (EMT)-related genes, including the epithelial marker E-cadherin and mesenchymal markers N-cadherin, vimentin, ZEB1, and SNAIL, which are involved in cancer metastasis." (PMID 32933177, 2020). "In addition, ajoene S-thiolates vimentin at Cys328, disrupting the vimentin network, and hence exerts antimetastatic activity in human HeLa and MDA-MB-231 cancer cells." (PMID 32370538, 2020). "MDK-induced NF-κB also increased cancer cell proliferation through PI3K-Akt signaling and Hes1 triggered epithelial-to-mesenchymal transition via increased Vimentin and Snail levels, and decreased E-cadherin levels, which were not recovered by survivin expression under MDK knock down and hypoxia." (PMID 32847073, 2020).
cancer (continued). "Our results showed that the EMT marker E-cadherin expression was significantly increased, and N-cadherin as well as Vimentin was significantly decreased after knockdown of HHLA2 expression, suggesting that HHLA2 was involved in the cancer progression of human ccRCC by promoting EMT." (PMID 31015801, 2019). "PFD treatment reduced cancer cell migration and invasion by reducing the Integrin α6 and uPAR levels and suppression of the expression of epithelial-to-mesenchymal transition (EMT) factors, vimentin and Zeb1." (PMID 31492002, 2019). "In cancer, CSDE1 has been shown to regulate c-Fos, c-Myc, Pten, Rac1, or Vimentin." (PMID 31027221, 2019). "Interestingly, a previous study revealed that the expression levels of EMT proteins, such as vimentin and ZEB1, were also decreased in miR-139 transfected cancer cells." (PMID 31426807, 2019). "The EMT-related transcription factor slug, linked to cancer progression and BCSC activity, was upregulated in 231PTR cells compared to 231 cell model with no changes in vimentin levels." (PMID 30875891, 2019). "Indeed, the fatostatin treatment led to decreased SREBP1 expression as well as vimentin, ZEB1, and metastatic potential of both OE21 and OE33 cancer cells." (PMID 31861383, 2019). "Mesenchymal markers such as N‐cadherin and vimentin are also markers of EMT and cancer progression." (PMID 31448526, 2019). "The EMT induction in these spindle-shaped cancer cells was confirmed by the weak or negative staining of E-cadherin and the positive staining of vimentin." (PMID 30333907, 2018). "Simvastatin caused a rapid and profound perinuclear bundling of vimentin and reduced the area of the vimentin IF network relative to vehicle treatment without significant changes in vimentin protein solubility in invasive cancer cells." (PMID 29317699, 2018). "The initial results indicate that the CD45neg/EpCAMneg nucleated cell population in the blood samples of cancer patients might contain cancer-related cells, particularly EMT-transformed CTCs, as suggested by the high detection rate of vimentin gene expression." (PMID 30715062, 2018). "In addition, VIMENTIN is a marker for epithelial-mesenchymal transition (EMT) and is currently being evaluated as a potential target for anti-cancer therapy." (PMID 30024920, 2018). "Cancer cells expressed vimentin, cytokeratin, and ALDH1, and we noted a markedly different intracellular distribution of these proteins, highlighting their different cellular functions." (PMID 31164563, 2018). "Another phenomenon we observed is that, in NANOGP8 over-expressed cancer cells, expression of EMT signature genes such as TWIST1, PRRX1, ZEB, Vimentin, and N-caderin, was significantly up-regulates and expression of the epithelial marker E-caderin was reversely down-regulated." (PMID 29689047, 2018). "Interestingly, down-regulation of E-cadherin and increased vimentin and N-cadherin expression were observed in CLCA4 silenced cancer cells." (PMID 30312171, 2018). "Vimentin is the major cytoskeletal component of mesenchymal cells, which is often used as a marker of mesenchymal-derived cells or cells undergoing an EMT during cancer metastatic progression." (PMID 29435142, 2018). "Twist most likely is not responsible for the upregulation of vimentin, as it was also expressed in vimentin-negative carcinomas." (PMID 29976164, 2018). "Given that N-cadherin is a key marker for EMT and involved in cancer metastasis, we next demonstrated the effect of N-cadherin on EMT process through regulating the expression of other EMT-relevant proteins such as E-cadherin and Vimentin." (PMID 28042956, 2017). "Protein levels cancer stem-like biomarkers (CD133, ALDH1, Lgr5, E-cadherin, Vimentin, Snail1) were also tested, indicating that the expression of CD133, ALDH1, Lgr5, Vimentin and Snail1 in the 131I-AC133.1 mAb group were lower than the other groups, while the level of E-cadherin was higher." (PMID 28430648, 2017).